CXCL8 (C-X-C motif chemokine ligand 8)
Diseases named in the same sentence as CXCL8 in open-access papers (continued):
Sharing a sentence is not in itself a finding about the gene and the disease.
infection (continued). "Infection of epithelial cells resulted in significantly increased secretion of the neutrophil chemotactic CXCL8 and IL-6, but no secretion of monocyte chemotactic CCL2 or TNF-α was observed." (PMID 22058091, 2012). "Proinflammatory cytokines CXCL8 and CXCL5 are chemoattractants for neutophils, IL-1α and IL-1β are important proinflammatory cytokines and would be expected to be increased early in infection." (PMID 22331987, 2010). "Infections with pso variants (especially with the HK2 variant lacking O-Ag biosynthesis) activated endothelial cells with abundant expression of cell adhesion molecules (ICAM-1 and VCAM-1) and inflammatory mediators (CCL2, CXCL1, CXCL8, CCL20, and IL-6)." (PMID 40570043, 2025). "BR15 infection induced a modest but statistically significant increase in TNF-α expression (p < 0.05) and a significantly higher expression of IFN-β1, IL-1β, IL-6, and IL-10, as well as the chemokines CCL2 (MCP-1), CCL5 (RANTES), and CXCL8 (IL-8), compared to MR766-infected cells." (PMID 40732762, 2025). "Moreover, upregulation of CXCL8 and BIRC3 were rescued by infection of HIV-1 ∆Vpr + Vpr." (PMID 39269169, 2024). "Notably, CXCL8 and CCL20 are induced early during vaginal SIV infection in macaques followed by secondary inflammatory process likely driven by CCL5 and other CK-producing cells, leading to recruitment of immune cells and fueling infection." (PMID 35051209, 2022). "CXCL8, also known as IL-8, has no homologs in rats or mice and is a significant component of inflammation-mediated processes as it attracts neutrophils, basophils, and T cells to the site of infection and promotes endothelial cell migration and proliferation." (PMID 35355981, 2022). "ONNV failed to increase CCL2 and CXCL8 protein levels at 24 h and also at 30 h post infection." (PMID 36611893, 2022). "In addition to CXCL8, SpyCEP cleaves all neutrophil-specific chemokines that possess an ELR motif, namely, CXCL1, CXCL2, CXCL3, CXCL5, CXCL6, and CXCL7, thereby inhibiting the recruitment of neutrophils to sites of infection and inflammation." (PMID 34649250, 2022). "In addition, CXCL8 could be induced by HBV directly and induces HBV replication in turn contributing to the persistence of infection." (PMID 33623529, 2021). "Among these immune related genes, we found an increased expression of CXCL8 or Interleukin-8, a chemokine involved in the migration of mature neutrophils to the site of infection in most myeloid cell subsets, and almost no expression in lymphoid populations and monocytoid precursors." (PMID 33345622, 2021). "In vitro infection of human NK cells by A. fumigatus hyphae for 6 h increases the secretion of inflammatory cytokines, such as IFN-γ, TNF-α, and growth factor GM-CSF, as well as several chemokines, including CXCL8/IL-8, CCL3/MIP-1α, CCL4/MIP-1β, and XCL1/lymphotactin." (PMID 34575791, 2021). "The cytokines CXCL8, CCL5 (also known as Regulated on Activation, Normal T Expressed and Secreted, RANTES), tumor necrosis factor α (TNF-α), CXCL1/5 and CCL3 released, promote development of a pro-inflammatory state along with the recruitment of other immune cells to the site of infection." (PMID 33102253, 2020). "Likewise, in SARS-CoV-infected aged macaques, administration of pegylated IFN-α intramuscularly on days 1 and 3 post infection ameliorated lung pathology and dampened CXCL8 induction without affecting viral burden in the lung." (PMID 33613280, 2020). "Further guidance to sites of infection is provided by a family of CXCL8 chemokines originating from concentrated sites of PAMPs and DAMPs, including CXCL1, CXCL2, CXCL3, CXCL5, CXCL6, CXCL7, and CXCL8 (IL-8), which are sensed by CXCR1 and CXCR2 on neutrophils and monocytes." (PMID 30791481, 2019). "However, another study performed using the hRSV Long strain showed that CXCL8 levels were not changed upon infection with hRSV, while CCL3 and CCL5 levels were increased." (PMID 30936869, 2019).
infection (continued). "For example, infection of human embryonic neural progenitor cells with JCPyV resulted in significant upregulation of the cytokines/chemokines such as CCL5/RANTES, GRO, CXCL1/GROα, CXCL16, CXCL8/IL-8, CXCL5/ENA78, and CXCL10/IP-10 and the chemokine receptor CXCR2." (PMID 31408949, 2019). "CXCL8 was not released in the culture media between −4 and 0 h of mock infection time." (PMID 28959685, 2017). "The difference in the profile of the cytokine response between cells infected with live H5N1 and those exposed to inactivated virus suggests that components of the viral envelope can initiate expression of IL-6 and CXCL8 independent of infection or viral replication." (PMID 28494003, 2017). "In order to investigate if an infection with P. acnes type IA or II could modulate the secretion of pro-inflammatory mediators from prostate cells, the concentrations of IL6 and CXCL8 were measured in cell-media from cells infected with P. acnes and compared to uninfected cells." (PMID 27284286, 2016). "Interestingly, the level of CXCL8 in the rectal fluids before SIVmac239wt challenge correlated with the plasma SIVmac239wt VL 2 weeks post-SIVmac239wt infection and this was independent of HSV-2 status." (PMID 26886938, 2016). "However, despite no TLR4 function, infection of hESC-EC with live Haemophilus influenzae induced a concentration-dependent release of CXCL8." (PMID 24690886, 2014). "Subsequent to Th17 cell activation, an increase in IL-17 production at the early stages of infection may benefit the infected host by (i) inducing chemokines (IL8/CXCL8) that recruit neutrophils and (ii) promoting IL-22 mediated production of defensins at the site of infection." (PMID 24073293, 2013). "Conversely, infection of cells with RCAN1-4 lentivirus short hairpin (Sh) RNA which ablates RCAN1-4 protein expression, augmented the PGF2α-FP receptor activation of CXCL8 mRNA (P < 0.01) and protein (P < 0.01) confirming that RCAN1-4 is a negative regulator of CXCL8." (PMID 19819266, 2009). "It has been shown previously and in the present study that transcriptions of TNF, CXCL8, and CXCL10 in hBECs were induced upon A. fumigatus infection, which could help recruit neutrophils, phagocytes, and/or other immune cells to the sites of infection for fungal clearance." (PMID 37695039, 2023). "Differences in the nature of the infection such as in granuloma formation due to distinct modulation of host immune responses through active interference with CXCL8 function by S. mansoni but not S. japonicum, and S. mansoni-specific hepatotoxicity may determine alternative selection pressure." (PMID 36370291, 2023). "However, infection of alveolar epithelial cells and alveolar macrophages with SARS-CoV-2 results in these cells producing markedly elevated levels of cytokines or chemokines such as IL-6, IL-8, tumor necrosis factor (TNF)-α, and C-X-C motif chemokine ligand 8 (CXCL8), resulting in a cytokine storm." (PMID 35328761, 2022). "Additionally, our pathway analysis revealed seven genes, IL-4, IFNγ, TLR4, CXCL8, IL-18, CSF2 and TNFα, are involved in the morphological and behavioral changes of macrophages, monocytes, granulocytes, and dendritic cells (DCs) and their recruitment into infection sites." (PMID 34753991, 2021). "Finally, a marked increase in inflammatory chemokines MIP-1β/CCL4, MCP-1/CCL2, and IL-8/CXCL8, accompanied by an increase of inflammatory cytokines IL-15, IL-12, TNF-a, GM-CSF, and G-CSF, which was detected in the lung predominantly at day 7–9, the middle and late stage of infection." (PMID 33180882, 2020). "Consistent with the lack of effect on BR15 infection, AbII treatment did not significantly alter the levels of IL-1β, IL-6, IL-10, CCL2 (MCP-1), CCL5 (RANTES), or CXCL8 (IL-8) in BR15-infected cells." (PMID 40732762, 2025).
infection (continued). "In the first study carried out to evaluate circulating levels of CXCL8 during ASFV infection, results revealed no significant modulation in vivo of this chemokine after infection with either virulent (Benin97/1, Uganda) or attenuated (OURT88/3) ASFV isolates." (PMID 36680273, 2023). "In blood samples collected after the RV infection, PBMCs were more responsive to poly-IC and production of CXCL-10 (p < 0.002) and IFN-α (p < 0.001), but not CXCL-8, showed a significant time-dependent response to the RV16 infection." (PMID 36296939, 2022). "While not significantly upregulated following infection, transcription of ATF3, CXCL3, CXCL8, and PTGS2 was at least partially dependent on EGR1." (PMID 35746681, 2022). "In the context of MAP infection, our previous RNA-sequencing analysis revealed the downregulation of CXCL8/IL8 in the PB and ileocecal valve (ICV) of MAP-infected cattle, regardless of the stage of the infection." (PMID 36359162, 2022). "CXCL8 levels were significantly increased in the HCV-HCC group in SVR and non-SVR patients compared to HCV-infection SVR and non-SVR patients (p = 0.04 *, p = 0.012 *), respectively." (PMID 34680563, 2021). "Non-activated human macrophages respond to infection with Salmonella by secreting cytokines such as TNF-α, IL-12, and chemokines including IL-8 (CXCL8)." (PMID 29538403, 2018). "W. chondrophila stimulation of CXCL8 secretion in HEK293 cells indicates that TLR2, TLR4, NOD2 and NOD1 receptors are not essential to the innate immune response to infection." (PMID 27002636, 2016). "As shown inFigures 1(a) and 1(b), CXCL-8 mRNA and CXCL-10mRNA were expressed after infection with M. bovis BCG,and IL-4 reduced gene expression of CXCL-8 in M. bovisBCG-infected HEp-2 cells but not CXCL-10gene expression." (PMID 16864907, 2006). "Finally, NBD peptide delivery prior to VLP infection blocked Vpr WT and H71R-mediated BIRC3 and CXCL8 transcriptional activation, but not Vpr-induced DNA damage in primary human MDMs." (PMID 39269169, 2024). "Furthermore, plasmatic levels of CCL2, CXCL8, MIG, and IP-10 were elevated in patients with VL without clinical signs and symptoms, identifying them as robust markers of asymptomatic infection and therapeutic efficacy." (PMID 37999614, 2023). "On the other hand, we also hypothesized that pathways linked to growth factor signaling and IL-8 (CXCL8) would be dispensable, as our studies utilize a serum-free infection model and because F. tularensis-infection does not elicit PMN IL-8 secretion." (PMID 35873156, 2022). "Interleukin 8 (IL-8 or CXCL8), showed an higher expression by epithelial cells in response to the serotypes a (p < 0.0001), b (p = 0.0007) and c (p < 0.0001) compared with non-infected condition at 2 h of infection." (PMID 33802988, 2021). "Very little or no infection-related effects were detected for SDF-1α (CXCL12) and IL-8 (CXCL8)." (PMID 30467502, 2018). "Infection of human neutrophils with IAV treated at 56°C to denature the viral replicase but not HA suggested that infection alone, but not replication, is sufficient to stimulate the release of CXCL8 and CCL4 in human neutrophils." (PMID 28553293, 2017). "In addition, 1,25(OH)2D treatment enhanced secretion of CXCL8 (p<0.03) and CXCL10 (p<0.03) production, either in the presence or absence of infection." (PMID 24475177, 2014). "Furthermore, gene expression analysis was performed to investigate the involvement of certain receptors and intracellular signalling molecules following infection of keratinocytes with S. aureus, in the presence or absence of PLNC8 αβ, and to verify the results of IL-6 and CXCL8 on the mRNA level." (PMID 34131160, 2021). "In addition, these results suggest that, particularly in the case of CM Bs, whose inhibitory effect on trophoblast chemotaxis was not reversed by CXCL8 or CCL2 neutralization, other infection-induced mediators not evaluated in this study may be involved in the modulation of this chemotactic process." (PMID 40943115, 2025).
cancer (2,454 papers, 1997 to 2026). A tumor composed of atypical neoplastic, often pleomorphic cells that invade other tissues. "Research indicates that under glucose-deficient conditions, both CXCL8 mRNA and its protein IL-8 are elevated in cancer cells in an NF-κB-dependent manner." (PMID 40444100, 2025). "Chemokines such as CCL2, CCL5, CCL4, and CXCL8 have been implicated in the initiation and progression of cancer." (PMID 41200178, 2025). "Upregulation of CXCL8 expression exhibited an increased risk of cancer and poor prognosis of normal patients." (PMID 40839565, 2025). "The levels of both CXCL8 mRNA and its protein IL-8 in cancer cells under conditions of glucose deficiency were increased in an NF-κB-dependent manner." (PMID 39905539, 2025). "CXCL8 derived from cancer-associated adipocytes shows a synergistic effect on anti-tumor immune response by inducing CD4+ T cell and CD8+ T cell infiltration and upregulating CD274 expression." (PMID 40863244, 2025). "In the context of ESCA, elevated CXCL8 expression can promote chronic inflammation, which is a hallmark of cancer progression." (PMID 40087784, 2025). "Among the CXCR2 ligands, especially CXCL1 and CXCL8 have often been reported to be associated with cancer progression." (PMID 38750114, 2024). "This meta-analysis is the first publication to have conducted a systematic evaluation of the relationship between five CXCL8 polymorphisms and overall cancer risk." (PMID 38807156, 2024). "An additional 101 case-control studies focused on the CXCL8 -251 site polymorphism were excluded because this polymorphism has been widely reported the association with several kinds of cancer risk through meta-analysis." (PMID 38807156, 2024). "The CXCL8 +781 T/C allele was similarly associated with a higher risk of cancer among Caucasians [TT vs. TC + CC, OR = 1.320, 95%CI (1.046–1.666), Pheterogeneity = 0.375, P = 0.019]." (PMID 38807156, 2024). "In conclusion, the results of the present meta-analysis support a potential link between the CXCL8 -353 and +781 polymorphisms and an overall increase in cancer risk in the general population or in individuals of particular ethnicities." (PMID 38807156, 2024). "Many prior studies have focused on exploring the relationship between CXCL8 gene polymorphisms and the risk of cancer." (PMID 38807156, 2024). "The CXCL8 -353A/T polymorphism was associated with an increased overall cancer risk [A vs. T, odds ratio (OR) = 1.255, 95% confidence interval (CI) (1.079–1.459), Pheterogeneity = 0.449, P = 0.003]." (PMID 38807156, 2024). "These receptors are activated by multiple signaling molecules including CXCL-1, CXCL-2, CXCL-5, CXCL-8, and IL-8 released by various constituents of this environment, including cancer cells, immune cells, and cancer-associated fibroblasts." (PMID 38361931, 2024). "Gene expression of cancer-associated adipocyte pro-inflammatory markers CXCL8, CCL2 and IL-1β was increased in hADMSC treated with EVs." (PMID 37833751, 2023). "IL-8/CXCL8 is also thought to contribute to immune suppression that can underlie resistance to immune checkpoint therapy in cancer patients." (PMID 37174001, 2023). "Expression of CXCL8 is significantly higher in numerous types of cancers, and high expression of CXCL8 is significantly associated with shorter median overall survival in many kinds of cancers based on TCGA database." (PMID 35372515, 2022). "Another hallmark of cancer promoted by CXCL8 secretion is metastases and here we showed that CXCL8 mRNA expression was enriched in CRC patients with stage IV disease." (PMID 35879507, 2022). "Cancer-associated fibroblasts (CAFs) attract monocytes by secreting CXCL8 (IL-8) and subsequently contribute to M2 polarizations, which synergize with CAFs in suppressing the functioning of NK cells in CRC." (PMID 35935996, 2022).
cancer (continued). "Elevated serum IL-8 levels (also known as CXCL8) have been associated with a higher density of TANs (predominantly N2) and poorer response to immune checkpoint inhibitors in patients with advanced cancers." (PMID 34637051, 2022). "The RING finger gene 183 (RNF183), a CRC-associated gene, upregulates the expression of chemokine CXCL8 by the NF-κB pathway and promotes cancer cell growth, migration, invasion, and metastasis in vitro and in vivo." (PMID 35935996, 2022). "A study reported that fibroblast growth factor-2 (FGF-2), secreted by cancer-associated fibroblasts, stimulates CXCL8 release and results in pancreatic tumor progression." (PMID 36612163, 2022). "IL-8/CXCL8, produced by a variety of human cancer cells, causes NET formation from neutrophils and granulocytic myeloid-derived suppressor cells (PMN-MDSCs)." (PMID 35203640, 2022). "The CXC chemokines (e.g., CXCL1, CXCL2, CXCL3, CXCL5, and CXCL8) are significantly upregulated in most cancers and positively associated with cancer metastasis and chemo-resistance." (PMID 36612163, 2022). "Conclusive evidence showed that multiple human cancer types contain NETs, which had a positive association with CXCL8 and reduced CD8+ T-cell infiltration." (PMID 35011369, 2021). "A large-scale retrospective analysis demonstrated that serum CXCL8 levels are associated with increased monocyte and neutrophil infiltration as well as worse prognosis in advanced cancer patients with immune checkpoint inhibitors." (PMID 35011369, 2021). "Studies have shown that the ability of TPC-1 (RET/PTC) and BCPAP (BRAFV600E mutation) cell lines to secrete CXCL8 is significantly different since oncogene types also differ in cancer cells." (PMID 32626535, 2020). "This demonstrates that a high expression of CXCL8 is strongly associated with the infiltration of TAMs, and studies have shown similar findings in other cancers." (PMID 32201645, 2020). "Some of these chemokines such as CXCL1, CXCL5, CXCL6 and CXCL8 are produced at high levels by tumors cells, whereas some are also produced by blood cells, cancer associated fibroblasts or endothelial cells." (PMID 32727083, 2020). "CXCL8 signaling has also been implicated in a number of diseases including atherosclerosis, asthma, allergic rhinitis and various cancers." (PMID 30969964, 2019). "CXCL8, otherwise known as interleukin-8, has been implicated as a cancer growth factor, as well as a molecule that promotes cholesterol accumulation." (PMID 30568916, 2018). "Chronic inflammation is associated with cancer and CXCL8, one of the proinflammatory chemokines, promotes tumorigenesis, angiogenesis, and metastasis." (PMID 29147073, 2017). "Clinical studies indicate that high plasma level of CXCL8 observed in cancer patients is associated with poorer prognosis." (PMID 29147073, 2017). "Meanwhile, some studies 33, 34 show that CXCL8 promotes cancer progression and is linked to poor prognosis." (PMID 28745433, 2017). "This is the first evidence showing that IFNγ inhibits CXCL8 secretion in a BRAF V600e mutated cancer cell line." (PMID 27555670, 2016). "These are profoundly different according to cell-related (the specific genetic lesion of cancer cells) and condition-related (basal and stimulated secretion of CXCL8 in cells with the same genetic mutation) aspects." (PMID 27555670, 2016). "This is especially interesting since recent evidence suggests that CXCL8 is associated with progression of some cancers." (PMID 25372289, 2014). "The most prominent cytokines that have also been shown to be linked with cancer development were IL-6, IL-8 (CXCL8), GRO/GRO-α (CXCL1), GCP-2 (CXCL6), and TIMP-1." (PMID 20723242, 2010). "In various cancers, CXCL8 is typically overexpressed and associated with poor prognosis." (PMID 40573881, 2025).